FN1 (fibronectin 1)
Diseases named in the same sentence as FN1 in open-access papers (continued):
Sharing a sentence is not in itself a finding about the gene and the disease.
tumor (continued). "Collectively, the findings from the experiments suggest that the reduction in FN1 expression suppresses the proliferation of tumours cells and hinders malignant behaviours, such as cell movement, in vivo and in vitro." (PMID 37784253, 2023). "The differential expression of the identified hub-gene FN1 from GEO and TCGA was retrieved, which revealed that FN1 was significantly upregulated in tumor samples." (PMID 37056700, 2023). "FN1 is extravasated from the bloodstream into tissues and promotes tumor adhesion in response to increased IL-8 secretion." (PMID 35130902, 2022). "Using GEPIA, we discovered that the levels of RET and FN1 in tumor tissues were much higher than those in normal tissues." (PMID 36601474, 2022). "Regulate cancer metastasis formation through stimulating the tumor structure by regulating fibronectin 1 secretion, which is a key component of the ECM." (PMID 35707536, 2022). "High FN1 expression in PDAC tissues correlates with higher tumor weight, more advanced disease, and poorer prognosis after resection." (PMID 35216235, 2022). "We discovered that tumor tissue expresses FN1 at a higher level than neighboring tissue, and those genes coexpressed with FN1 have a poor prognosis." (PMID 36081567, 2022). "To examine the significance of upstream genes involved in STAT3 activation regulating properties of tumor spheroids, we knocked down FN1, ITGA5, JAK1, JAK2, LDB1, and LMO2 from the cells." (PMID 36359204, 2022). "Macrophage clusters from different tumor types were diverse; additionally, SPP1+, C1QC+, ISG15+, and FN1+ TAMs were primarily enriched at the tumor site." (PMID 35504878, 2022). "FN1 is often secreted by the mesenchymal compartment whereas collagen IV is commonly produced by tumor cells." (PMID 35296667, 2022). "This study sheds light on the critical role of FN1 in GC and possible links and mechanisms by which FN1 regulates tumor-infiltrating immune cells." (PMID 36081567, 2022). "Evolving lines of evidence have indicated that FN1 played a pivotal role in tumor cell proliferation, migration, invasion, and angiogenesis." (PMID 36389789, 2022). "FN1 is a key gene in the RB tumor, and various works have confirmed that FN1 has been recognized to support cell proliferation and migration because it is correlated with MYCN." (PMID 36362243, 2022). "Our study shows that FN1 expression is closely related to tumor-infiltrating immune cells including macrophages, NK cells, Treg cells, CD8+ T cells, and DCs." (PMID 36081567, 2022). "FN1 and ITGB1 also affect Overall survival rate, immune cell infiltration, tumor mutation burden and microsatellite instability in pan-cancer." (PMID 35979350, 2022). "Clustered stromal cells corresponded to endothelial cells (positive for PECAM1/CD31, VWF), normal fibroblasts (FN1, EGFL6), tumor-associated fibroblasts (TAFs; PDGFRA, ADH1B), and thymic epithelial cells (TECs; KRT19, S100A14)." (PMID 35869073, 2022). "Futhermore, FN1 was critical for regulating tumor metastasis and invasion, with its protein being a marker of epithelial mesenchymal transition (EMT)." (PMID 35991881, 2022). "FN1 was systematically reviewed by Gene Expression Profiling Interactive Analysis (GEPIA), Linked Omics, Tumor IMmune Estimation Resource (TIMER), and Kaplan–Meier (KM) plotter analysis." (PMID 36081567, 2022). "Because they resulted from cross-contamination between adjacent AOIs, genes like FN1 were removed from Tumor DEGs." (PMID 35986012, 2022). "The ECM is a major structural component of the tumor microenvironment, and FN1 and VTN are part of the group of glycoproteins that make the ECM a cohesive network linking cells together with other structural components." (PMID 35477343, 2022). "We demonstrated that HOXD11 is a novel therapeutic target mediated by miR-138-5p promoting tumor metastasis of PSCC via the FN1/MMP2/MMP9 molecular pathway." (PMID 36151071, 2022).
tumor (continued). "This study revealed the function of hsa_circ_0000285/miR‐1278/FN1 in the tumor growth, proliferation, invasion, and apoptosis of GC cells." (PMID 35535385, 2022). "Generally, tumours cells generate an excess amount of ECM like fibronectin 1 (FN1), fibroblasts, and collagen." (PMID 36267139, 2022). "Another study showed that NKp46, the receptor on NK cells, mediated the production of IFN-γ and the latter induced FN1 expression in tumor lesions to induce tumor metastasis." (PMID 35303800, 2022). "Several soluble mediators produced by ascites-derived TAMs, e.g., TGFß1 protein, tenascin C (TNC) and fibronectin (FN1), activated tumor cell migration." (PMID 35682890, 2022). "We found that FN1+ TAM was likely pro-tumor in RCC, as reflected by the high expression of a myeloid-derived suppressor cell signature and of M2 polarization genes." (PMID 36423636, 2022). "FN1 is a type of adhesion glycoprotein involved in the ECM function of tumor cells, including cell adhesion, proliferation, and migration." (PMID 35711921, 2022). "Several stromal and ECM proteins in Cluster-2, such as FN1, act as a barrier that blocks immune cells from infiltrating the tumor and generating effective anti-tumor immunity." (PMID 35173148, 2022). "Tumor cells in chemo-resistant samples showed higher expression of chemoresistance and proliferation related genes (FN1, LCN2, CD44, FEN1)." (PMID 36248860, 2022). "FN1 is also reported to stimulate the expression of various inflammatory factors in the tumor microenvironment, thereby highlighting the regulatory influence of this glycoprotein in major inflammatory cells." (PMID 35780190, 2022). "A number of studies have indicated the tumor-promoting properties of FN1 and CHD4 in various cancer cells, and these results were consistent with the GC data collected from the TCGA database." (PMID 35821222, 2022). "Recently, a study suggested that FN1 promotes cellular aggregate formation conferring anoikis resistance to tumor cells, and that pretreatment of exosomes with anti-FN1 antibodies attenuates the invasive ability of fibroblasts." (PMID 36092898, 2022). "Taken together, the result indicated the involvement of TGFβ via LAP-TGFβ, cell adhesion via CD44, and extracellular matrix via FN1 in the anti-tumor action of extracellular Hsp90ab1 and MSN." (PMID 34976221, 2022). "An intracranial GBM xenograft model showed that expression of FN1 promotes cell proliferation and resistance to ionizing irradiation, facilitates cell invasion and enhances angiogenic tumor growth." (PMID 34316711, 2021). "Our findings highlight the important role of FN1 expression in THCA, and suggest a potential correlation between FN1 expression and tumor-immune interactions." (PMID 35141255, 2021). "Fibronectin 1 (FN1) is a type of adhesive glycoprotein that is highly expressed in many tumour cells (gastric, thyroid, etc.)." (PMID 34225581, 2021). "In another study, intratumoral NK-derived IFNγ was shown to induce expression of fibronectin 1 in tumor cells, changing the tumor architecture and reducing metastases formation in vivo." (PMID 33801234, 2021). "Among the different ECM components, FN1 has been reported as a main driver of tumor progression by different mechanisms including the increase of growth factors signaling via integrin clustering." (PMID 33731188, 2021). "Mechanical changes promoted by FN1 folding and tumor stroma rigidity contribute to therapy cancer resistance." (PMID 33731188, 2021). "MiR-132 also reduced the levels of CD44 and FN1 expressions to promote lymphocytic mediated apoptosis of tumor cells." (PMID 34419060, 2021). "FN1, ITGA5, THBS2, and LAMA1 were associated with cell adhesion and metastasis, and the expression of TGFB1, COL4A1, COL4A2, and THBS2 inhibited tumor growth." (PMID 34370778, 2021). "In this study, miR-200b targets TIMP-2, miR-200c targets FN1 and both miRNAs act as tumor suppressor miRNAs." (PMID 34298609, 2021).
tumor (continued). "We selected FN1 in the present study for its potential role in tumor angiogenesis and metastasis reported in previous studies." (PMID 34746236, 2021). "Tumor cells have been reported to upregulate the expression of ECM proteins including FN1 to create a pro-tumor stromal environment; however, further investigations are needed to delineate the precise role of 9-cis RA in mediating changes in the TME." (PMID 34944824, 2021). "This is further supported by gene expression analysis, where CAFs isolated from Osm−/− tumours exhibited decreased inflammatory gene expression (e.g. Il6, Mmp3, Has2 and Osmr) but increased myofibroblast gene expression (e.g. Acta2, Itgav and Fn1)." (PMID 34921158, 2021). "Fibronectin 1 (FN1) is being increasingly considered as a part of tumor pathogenesis and contributes to various malignant behaviors in solid tumors." (PMID 34746236, 2021). "Our observation of the most-often recurring integration sites such as TERT and MLL4 in tumors as well as FN1 in non-tumor tissues is compatible with previous reports." (PMID 34209079, 2021). "We found that TENM1, FN1, and F12 are highly expressed in tumor tissue, while APOD and BTNL8 have a lower expression in tumor tissue." (PMID 34221185, 2021). "MMPs degrade collagen, fibrinogen, fibronectin (FN1), and others and in this way enable tumor cells to invade." (PMID 34298609, 2021). "These included C-X-C motif chemokine ligand 12 (CXCL12), c-Met, receptor tyrosine kinase-like orphan receptor 1 (ROR1), and fibronectin 1 (FN1), which are associated with activated neoplasia, invasion, migration, and metastasis." (PMID 34069906, 2021). "On the other hand, it is confirmed that increased expression of FN1 is involved in the promotion of epithelial–mesenchymal transition (EMT), which has been implicated in tumor invasion and metastasis." (PMID 34746236, 2021). "This crucial role in a physiological microenvironment is even more significant in tumors where the reprogramming of the stroma is accompanied by an up-regulation of ECM proteins and their receptors, with FN1 as an important component of the tumor matrisome." (PMID 33731188, 2021). "The resident stromal cells, activated by tumor cells, produce FN1 which sustains the recruitment of hematopoietic bone marrow progenitor cells which express the FN1 receptor α4β1 integrin, establishing the basis for a nascent metastatic niche." (PMID 33731188, 2021). "FN1 plays a crucial role in metastasis development in PTC by modulating the activity of tumor cell proliferation, migration, and invasion, and it is a valuable biomarker for the diagnostic prediction of LNM." (PMID 33669363, 2021). "Type B cultures are defined by a low capacity to grow as tumor spheres and to generate intracranial xenografts, and express mesenchymal-related genes including FN1 (Fibronectin), CXCL12, and PDGFRB (Platelet Derived Growth Factor Receptor β)." (PMID 34021259, 2021). "FN1 is a member of the FN family, and its expression in human malignancies and has a key role in tumorigenesis and tumor progression." (PMID 35141140, 2021). "Although the pivotal role of FN1 in regulating cell motility and tumor metastasis has been reported in numerous studies, there are still few reports about the relationship between HK2 and FN1 in cancer cells." (PMID 34758823, 2021). "Functionally, FN1 induces proliferation, adhesion, and invasion of tumor cells, contributing to the formation, adhesion, metastasis, and disaggregation of malignant tumors." (PMID 34746236, 2021). "Previous studies of HNSCC samples have revealed that FN1 is upregulated in the tumor stromal region and at the invasive front of the tumor." (PMID 34746236, 2021). "Expression of COL6A1-A3 and FN1 was high both in primary tumor and metastatic tissues, pre- and post-chemotherapy, while COL6A5-A6 and VTN expression was lower (primary tumor pre-chemo n = 32/post-chemo n = 13; metastatic tissues n = 55/n = 38)." (PMID 34162871, 2021).
tumor (continued). "The results revealed that the OVCAR3 cells did express FN1 at a higher level than the A2780 cells, which proved that FN1 plays an important role in cell migration and that a high level of FN1 expression indicates high tumor cell mobility." (PMID 34093898, 2021). "In all three cell lines, significantly increased mRNA expression of mesenchymal marker FN1 was detected in tumor cells sorted from co-culture of tumor cells and CAFs as spheroids compared to tumor cells grown as spheroids without CAFs." (PMID 33353547, 2020). "Immunohistochemistry (IHC) analysis using a fibronectin antibody with reactivity to mouse and human revealed a similar staining intensity in 501mel and WM266‐4 tumours despite a significant lower mRNA expression of human FN1 in 501mel tumours." (PMID 32145051, 2020). "MMP2 and FN1 genes were analyzed also in tumor cells cultured in 2D and extracted from the xenogeneic masses (mPDGFRα− fraction)." (PMID 33585217, 2020). "The FN1 gene also correlated with clinicopathological characteristics and showed an inverse relationship with tumor and lymph node classification." (PMID 33112827, 2020). "It has been already reported that co-overexpression of fibronectin 1 and lncRNAs, such as lnc-ABCA12-3 (ATP Binding Cassette Subfamily A Member 12-3), in ESCC tissues is associated with tumor expansion, metastasis, and patients’ poor prognosis." (PMID 32079295, 2020). "A bulk of oncogenic studies have focused on FN1’s intriguing overexpression in tumor tissue and its correlation with a poorer prognosis." (PMID 32630254, 2020). "FN1 assembled in the tumor stroma initiates a cascade of cellular signaling pathways beneficial to cancer progression." (PMID 32605311, 2020). "In summary, we revealed an overexpression of ECM components, which are associated with enhanced migratory capacities of tumour cells (TNC, FN1), resistance to chemotherapy (COL11A1, SPP1) and adverse outcome (COL11A1, TNC, FN1) in other primaries." (PMID 32878206, 2020). "Out of nine genes differentially expressed in our study, five are included in the PI3K-AKT pathway, with three of them—FN1, NGFR, and THBS1—being associated with tumor progression." (PMID 32093414, 2020). "In LTBP1 highly expressed ESCC tissues, the expression of FN1 was also very high in the stroma surrounding tumor nests." (PMID 32216815, 2020). "Of particular importance, preclinical and clinical trials using FN1-guided cancer therapies, e.g., the extra domain A and B (EDA/B) of FN1 variants specific to tumor, are areas of active investigation." (PMID 32605311, 2020). "We previously observed that in comparison to primary tumor cells, CTCs were more migratory and expressed greater levels of FN1, as well as its downstream effectors ITGB1 and SLUG." (PMID 32630254, 2020). "Since its discovery in 1974, FN1 has gained recognition for being a critical player in multiple aspects of cancer progression, including tumor cell migration, invasion, and metastasis." (PMID 32630254, 2020). "In contrast to our results, analysis of FN1 by IHC in PDAC tissues has demonstrated that this protein is abundant in the tumor microenvironment." (PMID 32886718, 2020). "FN1 is a ligand for various members of the integrin family, and FN1 is also related to the formation and development of numerous tumours." (PMID 33113804, 2020). "Previous studies in other malignancies have highlighted the controversial role of FN1 in tumor biology." (PMID 30736807, 2019). "NKp46-mediated IFNγ secretion increases the expression of fibronectin 1 (FN1) by tumor cells leading to ECM structural changes in the primary tumors and decreased metastasis." (PMID 32117199, 2019).
tumor (continued). "Although tumor cells produce FN1 themselves, stromal cells, such as CAFs, are indispensable for bulk FN1 assembly." (PMID 31106200, 2019). "Compared to the low FN1 expression group, the high FN1 expression group had significantly larger tumor size (P = 0.002), more advanced T stage (P = 0.039) and N stage (P = 0.009), and also worse AJCC stage (P = 0.003)." (PMID 30736807, 2019). "Ffibronectin-1 (FN1) showed the highest expression level in the tumor tissue transcriptome: 71,967, which was 10-fold higher than that in the paracancerous tissues transcriptome." (PMID 31182966, 2019). "ECM components are produced by tumor cells and stromal cells and include collagen, FN1, proteoglycans, hyaluronic acid, and SPARC." (PMID 30736807, 2019). "FN1 has been widely described in tumor progression and is a member of multiple hallmarks, such as cell adhesion, invasion, migration, growth, and cell death escape." (PMID 31695721, 2019). "Cancer-associated fibroblasts are the main source of FN1 and promote tumor invasion and migration by FN1 assembly." (PMID 30736807, 2019). "For example, CAFs exert contractile forces and mediate extracellular FN1 assembly mainly via integrin αvβ3, leading to increased FN1 fibrillogenesis and ultimately contributing to tumor invasion." (PMID 31106200, 2019). "Internalization of tumor-derived exosomes into mesothelial cells induced the expression of adhesion-related molecules, such as fibronectin 1 (FN1) and laminin gamma 1 (LAMC1)." (PMID 30925929, 2019). "When compared to the low FN1 expression group, the high FN1 expression group had significantly larger tumor size (P = 0.002), more advanced T stage (P = 0.039) and N stage (P = 0.009), and worse AJCC stage (54.0% vs 28.7% with stage III, P = 0.003)." (PMID 30736807, 2019). "Tumor growth recapitulates the basic wound healing program and shares many similarities, such as deposition and crosslinking of fibrin and FN1 and the recruitment of immune cells." (PMID 31106200, 2019). "In untreated mice the FUS-CHOP chimera was bound to the FN1 promoter in sensitive and resistant tumours." (PMID 31409911, 2019). "We found that FN1 expression in the tumor stroma is distributed differently in hybMENA11a-positive or -negative tumors (p = 0.03)." (PMID 29907768, 2018). "Recently, many studies have shown FN1 to be associated with a variety of tumor types, and that the expression of FN1 is increased in tumor tissues and cells." (PMID 30568862, 2018). "FN1 binds to its receptors such as integrins, inducing distinct signals to promote tumor angiogenesis and migration of PDAC cells." (PMID 29515771, 2018). "COL1A1 and FN1 are individual ECM genes and have been reported to be associated with tumor invasion and metastasis." (PMID 30237810, 2018). "For C90 tumor, the expression of only two genes, namely Pai1 and Plau, were significantly increased, while Hif1a and Fn1 genes were significantly decreased compared with that of G0 tumor." (PMID 29362374, 2018). "MMP2, MMP9 and FN1 (Fibronectin 1) play important roles in tumor metastasis and are closely correlated with the migration and invasion of tumor cells." (PMID 29100277, 2017). "A periacinar pattern and the accumulation of FN1 around tumor nodules and the surrounding fibrous capsule have been also observed in HCC." (PMID 28842594, 2017). "Another report suggests that tumor cells produce FN1 and shed surface FN1, contributing to the increasing levels of FN1 in plasma or ascitic fluid." (PMID 28842594, 2017). "Neuropilin-1 (NRP-1) promotes α5β1 integrin-dependent FN1 fibril assembly and tumor growth by aiding myofibroblasts and soluble FN1 interactions." (PMID 28842594, 2017). "The most frequently identified fusion transcript in our dataset was FN1 (8/42, 19%); however, the frequency was biased towards normal samples (7 and 1 occurrence in normal and tumor tissues, respectively)." (PMID 29212479, 2017).